TXNRD1 (thioredoxin reductase 1)
Diseases named in the same sentence as TXNRD1 in open-access papers (continued):
Sharing a sentence is not in itself a finding about the gene and the disease.
prostate carcinoma (13 papers, 2012 to 2025). A carcinoma that arises from epithelial cells of the prostate gland. "We have previously reported that TXNRD1 had statistically significant higher levels in breast, head and neck, lung, and prostate cancer patients with poor prognosis." (PMID 35158912, 2022). "Recently, helenalin was found to target thioredoxin reductase-1 (TrxR1) in human prostate cancer cells, suppressing TrxR1 expression in these cells." (PMID 34680439, 2021). "On the other hand, TXNRD1 gene expression also increased the sensitivity of cell lines to irofulven, which is used to treat ovarian and prostate cancer." (PMID 33706760, 2021). "Supporting this effect of SNPs on PCA survival, tagSNPs in TXNRD1 (rs10778322, rs1128446, rs4964785) and GPX4 (rs2074452) were shown to be modestly associated with risk of mortality by prostate cancer." (PMID 25988760, 2015). "In the present study the utility of GPx1 and thioredoxin reductase 1 as in vitro selenium biomarkers was assessed in three different prostate cancer cell lines and the effects of selenium treatment on migration and invasion of PC3 cells was investigated." (PMID 24066278, 2013). "The study extended earlier work by showing consistent significant interactions between serum markers of Se status and TXNRD1, TXNRD2 and SELK genotype with respect to risk of high-grade or advanced stage prostate cancer." (PMID 23133653, 2012). "The observation that SNPs in both TXNRD1 and TXNRD2 genes are affecting prostate cancer risk supports the proposed role of the corresponding proteins in prostate function and/or tumour development." (PMID 23133653, 2012). "Moreover, IBC has been found to induce ROS-mediated apoptosis by targeting thioredoxin reductase 1 (TrxR1) in human prostate cancer." (PMID 34208562, 2021). "Increased nuclear TXNRD1 levels were found in high-grade, versus low-grade, human prostate cancers, and correlated with prostate cancer progression and androgen-deprived castration-resistant prostate cancer (CRPC) cells, suggesting that CRPC possesses an enhanced dependency on TXNRD1." (PMID 32933107, 2020). "The link between SNPs in TXNRD1-2 and SEP15 and prostate cancer incidence was recently supported by evidence that an association between genetic variants in these genes and risk of high-grade prostate cancer and prostate cancer recurrence." (PMID 25988760, 2015). "Thus overall, the data from this EPIC-Heidelberg nested case-control study indicate that together Se status and GPX1, SEPP1, TXNRD1, TXNRD2, and SELK genotype significantly alter risk of high-grade or advanced stage prostate cancer in a population with suboptimal Se intake." (PMID 23133653, 2012). "There were significant interactions between Se status and TXNRD1, TXNRD2 and SELK genotype with respect to high-grade or advanced stage prostate cancer, so emphasising the importance of the combination of Se intake and genotype in determining prostate cancer risk." (PMID 23133653, 2012). "In conclusion, this study shows a significant interaction between serum markers of Se status and TXNRD1, TXNRD2 and SELK genotype with respect to high-grade or advanced stage prostate cancer." (PMID 23133653, 2012).
pancreatic cancer (11 papers, 2020 to 2025). "In pancreatic cancer cells, loss of TXNRD1 results in increased abundance of GPX4 protein, and confers protection from ferroptosis." (PMID 35805147, 2022). "The cytoprotective function of TXNRD1 is particularly significant in cancer, where its overexpression is frequently observed across multiple malignancies, including lung, breast, and pancreatic cancers." (PMID 41333220, 2025). "TXNRD1-mediated antioxidant effects enhanced malignancy of pancreatic cancer cells through antagonizing ferroptosis." (PMID 36211509, 2022). "The only exceptions were (i) GPX2, whose high expression levels correlated with OS in breast and head and neck cancers; and (ii) TXNRD1, whose high expression levels correlated with poor OS in head and neck, kidney, liver, and pancreas cancers." (PMID 32933107, 2020). "In agreement with our data, authors also observed that depletion of TXNRD1 also conferred sensitivity to Napabucasin in pancreatic cancer cells." (PMID 32007910, 2020). "Similarly, in pancreatic cancer, the thioredoxin system, of which TXNRD1 is a key component, enables cancer cells to evade oxidative stress-induced cell death." (PMID 41333220, 2025). "Recently, it was shown that TXNRD1 is a strong negative modulator of ferroptosis susceptibility in pancreatic cancer cells." (PMID 35008976, 2022). "In addition, diaphanous-related formin-3 (DIAPH3) also upregulated cellular Se level and selenoprotein, TXNRD1, in pancreatic cancer cells." (PMID 36211509, 2022).
glioblastoma (10 papers, 2017 to 2025). The most malignant astrocytic tumor (WHO grade IV). "In terms of overcoming drug resistance, glioblastoma cells can mediate TMZ resistance through thioredoxin reductase 1 (TrxR1), while the small molecule inhibitor BS1801 relieves TMZ resistance by targeting TrxR1 and increasing the level of reactive oxygen species." (PMID 41201287, 2025). "Our results showed that in ferroptotic glioblastoma cells, new enhancer–promoter loops might induce upregulation of TXNRD1." (PMID 37834393, 2023). "We reckon that some rescue pathways may simultaneously work in ferroptotic glioblastoma cells, or complex functions of TXNRD1 in the regulation of ferroptosis work in different kinds of cells or at different cell stages." (PMID 37834393, 2023). "Western blot was performed to validate the expression levels of HDM2 and TXNRD1 in control and U87MG glioblastoma cells that were treated with 10 μM Erastin for 72 h." (PMID 37834393, 2023). "The expression of TXNRD1 was significantly higher in IDH wildtype, 1p/19q non-codeletion, MGMT unmethylation glioblastoma patients in both databases." (PMID 40914135, 2025).
glioma (10 papers, 2017 to 2025). A benign or malignant brain and spinal cord tumor that arises from glial cells (astrocytes, oligodendrocytes, ependymal cells). "The up-regulation of thioredoxin reductase-1 (TrxR1) is detected in more than half of gliomas, which is significantly associated with increased malignancy grade and recurrence rate." (PMID 28338004, 2017). "By comparing genomic differences between primary and recurrent glioma patients, Thioredoxin reductase 1 (TrxR1) was identified as a crucial role in TMZ resistance." (PMID 40914135, 2025). "Glioma cells elevate the expression level of TXNRD1 to against TMZ-induced reactive oxygen species (ROS), thereby conferring TMZ resistance." (PMID 40914135, 2025). "•Large-scale sequencing data identifies TXNRD1 is a key factor of temozolomide resistance in recurrent glioma patients." (PMID 40914135, 2025). "To further investigate TXNRD1-related biological functions in gliomas, we performed GO and KEGG analysis." (PMID 40914135, 2025). "TXNRD1 is predicted to be a vulnerability present across all glioma subtypes, and its expression was shown to highly correlate to AST and ODG patients’ survival." (PMID 38701414, 2024). "Since TXNRD1 is a gene encoding thioredoxin reductase 1 (TrxR1), which can maintain the reduction level of cells, we speculate that TXNRD1 is closely related to TMZ resistance in glioma." (PMID 40914135, 2025). "Furthermore, 33 single drugs, mainly antimetabolites and TXNRD1-inhibitors, as well as 17 drug combinations were predicted as potential candidates for gliomas." (PMID 38701414, 2024). "In an orthotopic mouse model using U87MG glioma cells, TIGAR knockdown prolonged the survival of tumor-bearing mice and enhanced the radiosensitivity of xenografts overexpressing thioredoxin reductase-1 (TRXR1)." (PMID 30823646, 2019).
lung adenocarcinoma (9 papers, 2008 to 2024). A carcinoma that arises from the lung and is characterized by the presence of malignant glandular epithelial cells. "First, we compared the cytotoxic effects of the three compounds in lung adenocarcinoma A549 cells, which have an unusually high activity and expression of TXNRD1 that is also known to be able to modulate the cytotoxic efficacy of different anticancer drugs." (PMID 37087975, 2023). "The effect was the most pronounced for lung adenocarcinoma, for which the median survival time decreased from 102 months (low TXNRD1 expression) to 44 months (high TXNRD1 expression)." (PMID 30791480, 2019). "Importantly, survival in lung adenocarcinoma (LUAD) did not significantly segregate by GPX4, TXNRD1 or combined GPX4 and TXNRD1 expression suggesting a function for redox pathway plasticity in determining patient outcome to be a unique feature of SCLC." (PMID 33824345, 2021).
rheumatoid arthritis (9 papers, 2016 to 2025). A chronic, systemic autoimmune disorder characterized by inflammation in the synovial membranes and articular surfaces. "We selected auranofin, an FDA-approved treatment for rheumatoid arthritis, which has been shown to inhibit thioredoxin reductase 1, an antioxidant enzyme that acts on electron cycling in the NADPH/GSH electron coupling system." (PMID 40371988, 2025). "Recently, auranofin (AF), a gold(I)-containing thioredoxin reductase 1 (TrxR1) inhibitor, has been used clinically to treat rheumatoid arthritis." (PMID 28300829, 2017).
colorectal cancer (7 papers, 2012 to 2025). A primary or metastatic malignant neoplasm that affects the colon or rectum. "Interestingly, variations in genes coding for the biosynthesis of selenoproteins, such as rs11111979 for TXNRD1, were found to modify the risk of colorectal cancer development." (PMID 40690813, 2025). "This study aimed to investigate thioredoxin reductase-1 (TrxR-1) expression, which has been related to disease progression in various cancers, for an indication of fibroblast-inducing colorectal cancer progression and metastasis." (PMID 36612053, 2022). "We suggest thioredoxin reductase-1 as a potential biomarker that can indicate the high proliferative fibroblast-induced-aggressiveness of HCT116 colorectal cancer cells in vitro and in vivo in adult zebrafish models." (PMID 36612053, 2022). "We evaluated the association between genetic variation in TXNRD1, TXNRD2, TXNRD3, C11orf31 (SelH), SelW, SelN1, SelS, SepX, and SeP15 with colorectal cancer risk." (PMID 22615972, 2012). "Therefore, lowering the number of bacteria that produce LPS with FMT may aid in blocking the actions of TXNRD1 and TXN1, encourage oxidative stress-induced damage to cancer cells, and thereby stop the onset and progression of colorectal cancer." (PMID 39619695, 2024).
myeloma (7 papers, 2015 to 2024). "Thioredoxin reductase 1 (HGNC symbol: TXNRD1) upregulation has been linked to Bortezomib resistance via upregulation of NF-κB-regulated genes in myeloma cells, as well as the upregulation of heat shock proteins and related genes in several cancer types." (PMID 31063487, 2019). "Components of the Trx system (Trx1 and thioredoxin reductase 1 (TrxR1)) are regulated by the Nrf-2 transcription factor and are highly expressed in various cancers including blood cancers, such as multiple myeloma and lymphoma." (PMID 32138149, 2020). "Most of the protein hits could be identified in blood samples according to the HPA database; two of them, namely DPEP1 and SOST, were classified by HPA as upregulated in BC; and five of them were found to be upregulated in leukemia and myeloma: SOST, TXNRD1, PKLR, EPHA2, PLIN3." (PMID 38791048, 2024).
selenium deficiency (7 papers, 2012 to 2024). A nutritional deficiency disease resulting from inadequate selenium levels in the body, which can lead to impaired function of selenoproteins essential for antioxidant defense and thyroid hormone metabolism. "In addition, it has been proposed that Txnrd1 suppresses the activation of Nrf2; inactivation of Txnrd1 with inhibitors or by selenium deficiency leads to the activation of Nrf2 signaling." (PMID 34579115, 2021). "However, even though GPX4 and TXNRD1 expression were both decreased after 72 h of selenium deficiency, there was no increase in NQO1 activity or protein under these conditions." (PMID 39456464, 2024).
epilepsy (6 papers, 2021 to 2025). A brain disorder characterized by episodes of abnormally increased neuronal discharge resulting in transient episodes of sensory or motor neurological dysfunction, or psychic dysfunction. "Additionally, the TXNRD1 gene plays a role in detoxifying ROS and managing redox signaling, making it a potential factor in epilepsy, which is often caused by increased oxidative stress in the brain." (PMID 37048057, 2023). "In a PTZ seizure mouse model for evaluation of epilepsy, the protein expression levels of thioredoxin-1 (TRX1), thioredoxin-like 1 protein (TXNL1), and thioredoxin reductase 1 (TXNRD1) were upregulated in the cortex of both acute and chronic groups." (PMID 40943128, 2025).
ovarian carcinoma (6 papers, 2018 to 2024). A malignant neoplasm originating from the surface ovarian epithelium. "In our prognostic model, we identified TXNRD1 as a risk factor for ovarian cancer patients." (PMID 29910195, 2018). "We constructed a three-gene prognostic signature consisting of TXNRD1, GLA and GSTZ1 which was associated with overall survival for ovarian cancer patients received platinum-based chemotherapy, especially in those with elder age, high pathological grade and advanced tumor stage." (PMID 29910195, 2018). "In the present study, we, for the first time, identified a panel of three oxidative stress-related genes, including TXNRD1, GLA and GSTZ1, to predict overall survival for ovarian cancer patients." (PMID 29910195, 2018). "However, the prognostic value of TXNRD1 in ovarian cancer has not yet been investigated." (PMID 29910195, 2018).
chronic myeloid leukemia (5 papers, 2015 to 2024). "TXNRD1 is a crucial regulator that plays a significant role in the ferroptosis of chronic myeloid leukemia cells." (PMID 37736497, 2023). "A previous study indicated that TXNRD1 was obviously upregulated in chronic myeloid leukemia cells after cysteine depletion." (PMID 36906552, 2023).
lymphoma (5 papers, 2020 to 2023). A malignant (clonal) proliferation of B- lymphocytes or T- lymphocytes which involves the lymph nodes, bone marrow and/or extranodal sites. "Seven selenoproteins, that included TXNRD1, GPX1, GPX4, SELENOH, SELENOO, SELENOS and SELENOT, were detected in both lymphoma-derived and primary CD4 T cells." (PMID 35163318, 2022). "Finally, when comparing these donor-derived CD4 T-cells with lymphoma-derived cell lines, common features emerged, most notably the high expression of GPX4, TXNRD1 and SELENOT transcripts." (PMID 35163318, 2022).
Ataxia (4 papers, 2008 to 2024). Ataxia refers to impaired coordination of voluntary muscle movement. "Furthermore, nervous system-specific knockout of Txnrd1 in mice leads to smaller body size with ataxia and tremor while mice deficient in Txnrd2 develop normally." (PMID 27656880, 2016). "By contrast, NS-specific Txnrd1 knockout mice exhibit reduced weight gain from P7 onwards and developed severe ataxia, suggestive of major cerebellar defects." (PMID 18350150, 2008). "A study using mice with nervous system specific (NS-specific) deletion of TXNRD1 and TXNRD2 demonstrated while NS-specific TXNRD2 null mice develop normally, mice lacking TXNRD1 in the NS are significantly smaller and display ataxia and tremor." (PMID 30677045, 2019). "While NS-specific Txnrd2 null mice develop normally, mice lacking Txnrd1 in the NS were significantly smaller and displayed ataxia and tremor." (PMID 18350150, 2008).
breast tumors (4 papers, 2010 to 2025). "For example, persistent OE19 cells displayed a high level of the thioredoxin reductase 1 (TXNRD1), a key redox mediator essential to re-activate dormant breast tumour cells and promote recurrent tumour formation." (PMID 40473905, 2025). "Pair-wise mRNA expression correlation analysis in human breast tumors from TCGA cohort showed a positive correlation between ZMYND8 and antioxidant genes including NQO1, GPX2, GCLC, GCLM, TXNRD1, and SRXN1." (PMID 38488001, 2024). "Further, it suggests that TXNIP and TXNRD1 are ERBB2 effectors whose multiple cellular functions contribute to proliferation, apoptosis resistance, metabolic reprogramming and, finally, to the hallmarks of ERBB2-positive breast tumors." (PMID 20584310, 2010).
colitis (4 papers, 2014 to 2025). Inflammation of the colon. "For example, Lactobacillus fermentum Lf1 increased the expression of Nrf2 and downstream antioxidant enzymes such as SOD2 and thioredoxin reductase 1 (TrxR-1), while reducing lipid peroxidation in a DSS-induced colitis model." (PMID 41462607, 2025). "Interestingly, IHC staining results revealed that, except for TXNRD1, the expression levels of ACSL4 and LPCAT3 in colitis mice were higher than those in the normal control group, while SLC7A11 and GPX4 displayed the opposite consequence." (PMID 40691131, 2025).
Alzheimer disease (3 papers, 2008 to 2025). A progressive, neurodegenerative disease characterized by loss of function and death of nerve cells in several areas of the brain leading to loss of cognitive function such as memory and language. "Both been implicated in Alzheimer's disease, with TXNRD1 showing a consistent upregulation in Alzheimer's disease, while the changes in PRDX3 were more variable." (PMID 40491829, 2025). "In future experiments, our models might prove most suitable to investigate the role of the Txn1/Txnrd1 system in animal models of Alzheimer's Diseases or other neurodegenerative diseases." (PMID 18350150, 2008).
astrocytomas (3 papers, 2017 to 2022). "An analysis of 433 astrocytomas has indicated that thioredoxin reductase 1 (TrxR1) becomes up-regulated in more than 66% cases, which is significantly associated with higher proliferation activity and worse prognosis." (PMID 28338004, 2017).
diabetes (3 papers, 2013 to 2022). "Several components of the thioredoxin system are closely linked to LRRK2, including PRDX3, TXNIP, and TXNRD1, which have been identified in recent years as risk factors for obesity and diabetes in human subjects, and as nutrient sensing mechanisms and controlling factors of adipogenesis in mice." (PMID 23799078, 2013). "Methylglyoxal is a well-described GDP in PD fluids and diabetes mellitus, and may impair the TXN/TXNRD1 and glutathione reductase (GSR) system in several cell types including aortic endothelial cells." (PMID 35887356, 2022).
esophageal squamous cell carcinoma (3 papers, 2020 to 2024). Esophageal squamous cell carcinoma (ESCC) is a type of esophageal carcinoma (EC) that can affect any part of the esophagus, but is usually located in the upper or middle third. "CircfNDC3B not only affects tumor cells through exosomal transfer but also functions through the miR-490–5p/TXNRD1 axis, further driving the progression of esophageal squamous cell carcinoma." (PMID 38933443, 2024).
hearing loss (3 papers, 2014 to 2025). "These three genes were: Hspb1 (p = *0.0345, F = 3.79, df = 2,29) and Gpx6 (p = **0.0011, F = 8.644, df = 2,29) that showed significant up-regulation and Txnrd1 (p = 0.6575, F = 0.4254, df = 2,29) that showed down-regulation with age and hearing loss." (PMID 24587312, 2014). "Genetics variants in TXNRD1 and WNT8A are notable risk factors for hearing loss and tinnitus, respectively." (PMID 35322580, 2022).
inflammatory bowel disease (3 papers, 2019 to 2022). A spectrum of small and large bowel inflammatory diseases of unknown etiology. "Previous study also showed that TXNRD1 reduced the oxidative stress during inflammatory bowel disease as well as inhibited intestinal inflammation." (PMID 36032298, 2022).